TLR9 (toll like receptor 9)
Diseases named in the same sentence as TLR9 in open-access papers (continued):
Sharing a sentence is not in itself a finding about the gene and the disease.
infection (continued). "The different functions of TLR2 and TLR9 observed explain the impact of their deficiency on the resistance to infection." (PMID 23650544, 2013). "This probably explained the susceptibility of TLR9−/− mice during the infection since TLR2 cannot assume IL-12/IL-23p40 production required for mice survival in such situation." (PMID 23650544, 2013). "We used in vitro and in vivo models of infection by P. brasiliensis, comparing wild type and TLR9 deficient (−/−) mice, to assess the contribution of TLR9 on cytokine induction, phagocytosis and outcome of infection." (PMID 23936560, 2013). "We analyzed the induction of IFN-γ and cytotoxic activity in vivo in TLR2-, TLR4-, TLR9- or MyD88-deficient mice during infection, and found intact responses compared to WT mice." (PMID 20442858, 2010). "This infection dose was 300-fold higher than that previously used with TLR9 deficient mice that are at least 100-fold more susceptible to ECTV infection." (PMID 20300179, 2010). "Previous bioinformatic studies have indicated that the genome of the human pathogen Chlamydia trachomatis contains TLR9 stimulatory motifs, and correlative studies have implied a link between human TLR9 (hTLR9) genotype variants and susceptibility to infection." (PMID 38370826, 2024). "Associations in the same direction between the TLR9 (rs352139) SNP and infection have been reported, including maternal CMV infection in a cohort of Zimbabwean pregnant women in which homozygous carriers of the minor C allele were at higher risk than homozygous for the reference allele." (PMID 35967300, 2022). "On the other hand, the presence of the minor risk alleles within the TLR9 SNPs—AG/GG for rs5743836 and TC/CC for rs352139—was associated with a decreased probability of remaining free from high-level infection during the first year (log-rank test P-values = 0.031 and 0.024, respectively)." (PMID 35967300, 2022). "Some works have shown the importance of TLR9 activation in opportunistic fungi, as well as C. neoformans, C. albicans and Aspergillus fumigatus, but the importance of this receptor in the infection caused by C. gattii is still poorly understood." (PMID 36145419, 2022). "To determine whether the loss of TLR2 and TLR9 alters infection-associated trabecular bone loss, we first performed baseline analyses of uninfected mice to rule out underlying differences in trabecular bone volumes within groups." (PMID 36226943, 2022). "The up-regulatory effect on MyD88 and TRIF may be the result of direct viral interaction or the up-regulation effect on cell-membrane- (TLR2 and TLR4) and endosomal-associated (TLR3, TLR8, and TLR9) TLRs induced by single-PDCoV infection." (PMID 36376395, 2022). "To test whether the loss of TLR2 and TLR9 reduces infection-associated osteoclastogenesis, we assessed osteoclast abundance relative to bone volume in the trabecular region using histomorphometry." (PMID 36226943, 2022). "Furthermore, detection of bacterial DNA from Spneu by TLR9 has been identified as an important receptor in the defence to pneumococci, as TLR9 deficient mice were highly susceptible to lethal infection." (PMID 36096803, 2022). "To determine whether the loss of both TLR2 and TLR9 alters bone homeostasis during infection, we performed μCT on infected femurs from WT and Tlr2/9−/− mice collected at 14 dpi." (PMID 36226943, 2022). "Thus, our results provide a better understanding of the immunomodulatory role of TLR9 in experimental infection caused by C. gattii." (PMID 33446850, 2021). "TLR4 rs4986790, rs1927911 and TLR9 rs187084 showed association with HPV 16/18 infection." (PMID 31278284, 2019). "Interestingly, TLR9 polymorphisms are associated with susceptibility to infection, with the T-1237C polymorphism that causes altered TLR9 expression, being predictive of susceptibility to CMV infection." (PMID 31636622, 2019).
infection (continued). "In vivo, mice deficient in Tlr9, cGas, or Sting blocked the production of type I IFNs and showed higher viral loads and serious pathology in the liver and spleen, and were more susceptible to lethality caused by infections with ECTV as compared with WT mice." (PMID 29963044, 2018). "Since IFN-γ−/− or IFN-γR−/− mice are more susceptible to infection with African trypanosomes than wild-type mice, it is conceivable that the early mortality of infected MyD88−/−, TLR9−/−, and IL-12p70−/− mice is attributed to, at least in part, the impaired capacity of synthesis of IFN-γ." (PMID 28936213, 2017). "The determined correlation suggested that direct interaction between T. gondii and TLR9 might trigger proinflammatory responses and, hence, led to severe pathologies such as ocular disease, associated with this infection in Brazil." (PMID 23161283, 2013). "Therefore, the susceptibility profile observed for TLR9−/− mice early after infection with P. brasiliensis likely associates with an exacerbated neutrophil recruitment to the site of infection and/or with a particular detrimental phenotype of neutrophils." (PMID 23936560, 2013). "Indeed Tlr9−/− and Tlr7−/− mice were shown to be more susceptible than WT mice to infection with the parasite." (PMID 22496959, 2012). "In addition, we protected highly susceptible TLR9-deficient mice with intranasal MVA immunization even two days after ECTV infection." (PMID 20300179, 2010). "However, in vivo, TLR9-/- mice were slightly more susceptible to L. amazonensis infection than WT mice, presenting a larger lesion and an increased parasite load at the peak of infection and in the chronic phase." (PMID 30802247, 2019). "However, before addressing this, we wanted to first determine whether loss of TLR9 had any impact on host defense against infection with H1N1 alone or MRSA alone." (PMID 30682165, 2019). "In the spleen, a reduction in TLR-4 transcription has been detected in infected groups compared to uninfected individuals, while in the skin during the earliest stages of infection, an increase in TLR-9 transcription was revealed." (PMID 40725420, 2025). "Understanding how these mechanisms operate across different infections is critical to refining our perspective on TLR9-mediated immunity." (PMID 40460068, 2025). "An in vitro infection of murine BMDMs isolated from TLR2-, TLR3- TLR4-, TLR7-, TLR9-, TLR2/TLR4-, and TLR2/TLR4/TLR9- deficient mice and cultured with Mtb showed that TLR9 was critical for protection against infection via FLT-3 ligand-generated DCs." (PMID 41236793, 2025). "Future research should focus on elucidating the diverse functions of the TLR9 activation and cooperation, particularly in the context of infections that exploit its signaling pathways." (PMID 40460068, 2025). "With infection, expression of certain PRRs in platelets increased (TLR9, RIG-I, and CGAS), while in leukocytes, they decreased (TLR6, TLR8)." (PMID 40825056, 2025). "Although TLR9 is typically regarded as a receptor mediating inflammatory responses, its role in inflammation control during infection by certain pathogens warrants further discussion." (PMID 40460068, 2025). "TLR9 signaling promotes the secretion of IL-12 by murine macrophages in response to in vitro infection with Mycobacterium tuberculosis and contributes to an adaptive Th1 immunity." (PMID 40646740, 2025). "We have previously reported that recognition of chlamydial species by TLR9 also occurs late in infection, and we proposed that chlamydial DNA is likely released due to random lytic events that occur during the transition from RBs to EBs9." (PMID 40502116, 2025). "Upon infection, epithelial cells and the resident immune cells recognize CT via pattern recognition receptors (PRRs), such as Toll-like receptor 9 (TLR9), triggering pro-inflammatory cytokine signaling cascades." (PMID 41226666, 2025).
infection (continued). "With infection, in platelets, associations changed and expression of F2RL3 and GP6 both positively correlated with TLR6, TLR9, RIG-I, MDA5, LGP2, and CGAS." (PMID 40825056, 2025). "We observed that M-CSF-differentiated BMDMs minimally expressed CD103 at baseline but showed robust upregulation after exposure to endosomal TLR ligands (TLR3, TLR7, TLR9) or infection with LCMV." (PMID 40630637, 2025). "Following a needle challenge, immunisation with autoclaved L. major (ALM) given with the Th1 adjuvant TLR9 agonist CpG oligodeoxynucleotides has been found to significantly protect against infection in resistant C57BL/6 mice." (PMID 39201440, 2024). "The cidal vs. static difference we observe in WT infections, however, was substantially reduced in Tlr9−/− iBMDMs." (PMID 39609397, 2024). "Type I interferon, MX3, and TLR9 genes were expressed in juvenile koi carp due to an infection with bacteria." (PMID 39483482, 2024). "In contrast, infection of TLR9-/-mouse macrophages NR-9456 with S. epidermidis 1457 elicited a significantly induction of IL1b expression, which was similar to IL1b expression after infection with 1457-M10 and 1457ΔatlE." (PMID 39567551, 2024). "As VFRA is more resistant to these killing processes, it would release less DNA and ssRNA in the lysosome, explaining the increase in TLR7 and TLR9 activation only with the Y strain infection." (PMID 39000601, 2024). "Another example is the pairwise cooperation of TLR8 with TLR7 or TLR9 within endosomal membranes to regulate the eukaryotic inflammatory response upon detection of viral nucleic acids produced during infection." (PMID 39131286, 2024). "In contrast, and in line with observations made using ODN TAAGGG to inhibit TLR9 activation in hMDM, infection of murine wild-type macrophages with S. epidermidis 1457 did not induce IL1b compared to the untreated control." (PMID 39567551, 2024). "We evaluated IFN responses to the TLR9 agonist CpG2216 simulating infection conditions, since activated pDCs are expected to stimulate the production of type I IFNs." (PMID 38257109, 2024). "Many sensor proteins (e.g., cGAS, AIM2, and TLR9) recognize the molecular signature of infection or stress and are responsible for the innate immune response to DNA." (PMID 38343534, 2024). "Inhibition of TLR9 resulted in slightly increased IL10 induction after infection with 1457-M10 and 1457ΔatlE." (PMID 39567551, 2024). "TLRs play a crucial role in preventing host invasion in pathogenic infections, and TLR2, TLR4 and TLR9 are involved in the defense against Salmonella in vivo." (PMID 39456517, 2024). "On the other hand, TLR9 induces cytokine production and activation of Th1 responses, and a triple defect in TLR3, 7, and 9 made mice more susceptible to the infection." (PMID 39000601, 2024). "This is expected to prevent disruption of immune homeostasis in SLE patients upon infection with pathogens containing ssRNA and dsDNA, providing new ways to target B-cell TLR9 to treat SLE." (PMID 36875095, 2023). "Collectively, these in vitro and in vivo studies point towards a novel mechanism of TLR-9 mediated immunoprotection during LdCen−/− infection." (PMID 37111420, 2023). "After infection with CyHV-2, the relative expression level of TLR9 mRNA dramatically upregulated in the intestine at 5 dpi and in the liver at 1–3 dpi." (PMID 38003793, 2023). "The addition of agonists to the intracellular TLRs, TLR7, TLR8 and TLR9, prior to infection in PBMCs has been shown to exhibit anti-HIV activity by inducing high levels of the type-1 interferons and interferon-stimulated genes." (PMID 38005883, 2023). "Studies demonstrated that TLR9 is important for the survival of mice during the first 48 hours of infection by P. brasiliensis." (PMID 38045758, 2023). "Our results also emphasize the importance of TLR-9 and NF-κB in LdCen−/− infection induced DC activation." (PMID 37111420, 2023).
infection (continued). "Next, we investigated the role of TLR-9 and its downstream NF-κB signaling pathway in eliciting DC function during LdCen−/− infection and compared it to LdWT infection." (PMID 37111420, 2023). "A down-regulation of the expression of CD209, a c-type lectin receptor found specifically in dendritic cells (DC), was observed only in the head-kidney of vaccinated animals early on infection in addition to the tlr9 inhibition." (PMID 37346045, 2023). "In this study, we investigated the function of TLR-9 during LdCen−/− infection and found that it increased the expression of TLR-9 on DCs and macrophages from ear-draining lymph nodes and spleen." (PMID 37111420, 2023). "To explore the existence of TLR-TLR crosstalk, we therefore treated wildtype and Tlr4−/− iBMDMs with inhibitors of TLR2 (CU CPT22), TLR3 (TLR3/dsRNA complex inhibitor), and TLR9 prior to infection with C. neoformans." (PMID 37580395, 2023). "The TLR9 level was increased significantly by 123%, p < 0.01 at 12 h compared to 6 h post infection." (PMID 36707891, 2023). "In this study, we analyzed the expression of TLRs 2, 4, and 9 in macrophages and DCs in response to LdCen−/− and LdWT infections and found an elevated expression of TLR-9 transcript in LdCen−/− infection compared to LdWT infection." (PMID 37111420, 2023). "Further, by examining the signaling events, we determined that silencing either MyD88 or TLR-9 reduces the production of proinflammatory cytokines in DCs during LdCen−/− infection." (PMID 37111420, 2023). "Eosinophils were more frequent in mixed inflammatory infiltrate from TLR9-/- infected mice than WT infected mice 21 days after infection." (PMID 36145419, 2022). "In that study, one SNP was found located within the TLR10 gene (TLR10_292 SNP), while in the current study five SNPs were found but in the TLR5 and TLR9 genes instead, also in Corriedale sheep but under natural infection." (PMID 36140716, 2022). "TLR9 is located in the apical compartment of the gastric epithelial cells in healthy controls and in the basolateral compartment in individuals with infections." (PMID 35408892, 2022). "In the present study, we showed that cryptococcal titan cells were observed in both WT and TLR9-/- mice 21 days after infection by C. gattii." (PMID 36145419, 2022). "We found functional memory B cells specific for SARS-COV-2 that were reactivated by polyclonal stimuli such as TLR9 activation in more than 80% of adults and in more than 60% of children with a history of infection." (PMID 36437276, 2022). "In the same way, in the early stages of a mouse model infection, TLR9 activation induced an anti-inflammatory cascade." (PMID 35408892, 2022). "Here we will focus on the contribution of mouse models to understanding the significance of GPI-TLR2 recognition and DNA/hemozoin-TLR9 recognition in the immunology of blood stage infections." (PMID 36146602, 2022). "TLR9‐/‐ infected mice exhibited progressive lesions and higher parasites burden during the acute phase of infection as compared to infected C57BL/6 WT mice." (PMID 35119120, 2022). "From this result, CD38 can be considered as the factor contributing to the expression of TLR9 after PPV infection." (PMID 35746608, 2022). "As for lethal infection and similar to TLR2, TLR9 sensing is a critical pathogenic factor in the development of ECM in the P. berghei ANKA model." (PMID 36146602, 2022). "This idea is supported by the observation that other viruses (Merkel cell polyomavirus, hepatitis B virus, and Epstein-Barr virus [EBV]) also interfere with TLR9 function during the maintenance phase of the infection (124, –, 126)." (PMID 35311536, 2022). "Most Ad typesuse CAR to enter cells, others CD46, a receptor presented in DC cells thatcontribute to its infection and together with Toll Like Receptor 9 (TLR9)activation induces these cells to produce IFN-α." (PMID 36206378, 2022).
infection (continued). "To investigate if a collection of different clinical H. pylori type-I (cagPAI-positive) and type-II (cagPAI-negative) isolates can activate TLR9, we performed infections of the HEK293 epithelial reporter cell system." (PMID 35239059, 2022). "Most importantly, this review explores and discusses the significance of TLR2 and TLR9 as a crucial factor in determining infection outcome across Leishmania species." (PMID 35119120, 2022). "We infected RANKL-primed BMDMs from WT, Tlr2−/−, Tlr9−/−, and Tlr2/9−/− mice and found that, for all genotypes, infection significantly increased osteoclast numbers compared to those observed in the vehicle." (PMID 36226943, 2022). "In these mice, GLY was able to protect the cornea by lowering clinical scores at both 3 and 5 days after infection and downregulating TLR9, HMGB1 and RAGE after infection." (PMID 36422579, 2022). "The lard diet group presented with an increased parasitic load in the heart and adipose tissues following infection as well as an increased expression of Tlr2 and Tlr9 in the heart." (PMID 34113663, 2021). "Other study using a transgenic mouse deficient for endosomal nucleic acid sensing TLRs (TLR3, TLR7 and TLR9) showed increased parasitism and bigger lesion after 6 weeks post infection." (PMID 34745100, 2021). "It has been reported that TLR9 activation is crucial for type I IFN induction following infection of DCs with the Gram-positive bacteria S. aureus infection in DCs." (PMID 34588221, 2021). "We also identified indirect targets of EBV miRNAs in B cells, such as TRL7 and TLR9, in the prelatent phase of infection." (PMID 33785626, 2021). "Various studies have shown that TLR9 is required for the innate immune response to infections with human DNA viruses, including HSV-2 and EBV." (PMID 34439137, 2021). "Immune cells mount an early TLR9/IFN-dependent response to abort the infection prior to the synthesis of viral proteins." (PMID 34071585, 2021). "To further investigate the clinical relevance of TLR9 SNPs and the outcome of infection, we determined the serum concentrations of target cytokines in HIV/CMV co-infected patients." (PMID 34572011, 2021). "Other researchers demonstrated that EBV uses TLR9 to infect B lymphocytes by inducing their proliferation in the initial phase of infection, while in the later phase it lowers TLR9 expression to escape an immune response." (PMID 34439137, 2021). "Trypanosoma cruzi experimental infection in TLR-deficient mice showed that TLR2, TLR4, TLR7, and TLR9 play a role in host resistance." (PMID 34336720, 2021). "The only TLR gene that was upregulated in this pathway was TLR9, which is activated by unmethylated CpG sequences in DNA molecules due to cancer, infection, or tissue damage." (PMID 34616397, 2021). "The TLR family member TLR9 is an endosomal receptor that recognizes unmethylated CpG motifs in pathogen DNA and provides protection against various infections but also can detect self-DNA during pathophysiological conditions." (PMID 34588221, 2021). "The expression of TLR2 mRNA was significantly increased on the 24th and 40th days after infection, and the expression of TLR9 mRNA on the 31st and 40th days after infection also showed an up-regulated trend." (PMID 34988138, 2021). "TLR9-/- mice are more susceptible after aerosol infection with 50–100 or 500 CFU MTB, although only infection with the high dose causes higher bacterial burden in lungs." (PMID 33503864, 2021). "Infection from HSV-2 also induces a TLR9-mediated type III IFN response in DCs that relies more on NF-κB rather than IRFs." (PMID 33791247, 2021). "This regulatory mechanism to control Pellino2 expression during TLR9 activation is likely to be necessary to maintain sufficient immune response to infection but, at the same time, limit damaging inflammation and autoimmunity." (PMID 34588221, 2021). "It is conceivable that EBV is sensed by TLR9 in B cells during their de novo infection, because of the unmethylated dsDNA." (PMID 33434416, 2021).